FABP5 (fatty acid binding protein 5)
Diseases named in the same sentence as FABP5 in open-access papers (continued):
Sharing a sentence is not in itself a finding about the gene and the disease.
breast carcinoma (continued). "In accordance, it has been shown that RA inhibits the growth of mammary carcinomas that express a high CRABP-II/FABP5 ratio but facilitates proliferation of mammary carcinomas in which this ratio is low." (PMID 20847935, 2010). "FABP5 and PPARβ/δ is involved in enhancing cell proliferation and survival in keratinocytes and some mammary carcinoma cells." (PMID 20847935, 2010). "Significant overexpression of transcript Zfp36l1 was found in lymph node and breast carcinomas, and increased Fabp5 expression induces metastasis in human prostate carcinomas." (PMID 19190631, 2009). "Our studies further support a pro-metastatic role for FABP5 in breast cancer progression." (PMID 40106183, 2025). "However, invasive breast cancer tissues exhibited a significant increase in FABP5 expression, mainly in tumor cells." (PMID 40106183, 2025). "For example, FABP5 is highly expressed in colorectal and breast cancer cells, upregulating fatty acid synthase (FASN) and sterol regulatory element-binding protein (SREBP) to drive de novo fatty acid synthesis, providing raw materials for cell membrane construction." (PMID 40717587, 2025). "For example, FABP5 can manage fatty acid absorption, and its higher expression on ER and PR receptor-negative breast cancer cells is linked to a poor prognosis." (PMID 37612627, 2023). "FABP5 is highly upregulated in breast cancer and enhances proliferation, migration, and invasion." (PMID 36338999, 2022). "However, identification of FABP5 as a biomarker in HER2-negative breast cancer requires substantially increased cohort size and mechanistic validation for robust interpretation." (PMID 34099718, 2021). "Besides, FABP5 promotes lymphatic metastasis in cervical cancer, prostate cancer progression, breast cancer progression, and KC differentiation by reprogramming fatty acid metabolism through the NF-κB signaling pathway." (PMID 34934042, 2021). "In contrast, Krüppel-like factor KLF2 inhibits FABP5 protein expression and subsequent PPARβ/δ activation and thus, might act as a tumor suppressor in breast cancer cells." (PMID 32375405, 2020). "Among the FABP isoforms, FABP4 and FABP5 likely play critical roles in mammary tumor development." (PMID 31941087, 2020). "Consequently, FABP5 in different mammary epithelial cell lines was assessed; FABP5 was more highly expressed in breast cancer cell lines with more aggressive phenotypes." (PMID 29914512, 2018). "Moreover, FABP5 silencing in Hs578T breast carcinoma cell line resulted in approximately 40% reduction in proliferation activity." (PMID 30384831, 2018). "Our results revealed that only FABP5 was expressed at a considerable level in breast cancer cells." (PMID 29914512, 2018). "We showed FABP5 plays a role in both breast cancer growth and metastasis." (PMID 25779666, 2015). "It was also reported that KLF2 suppresses the expression of FABP5 in MCF-7 mammary carcinoma cells." (PMID 26416422, 2015). "This role of host FABP5 promoting breast cancer has been previously reported." (PMID 25779666, 2015). "Thus, both CRABP1 and FABP5 represent potential therapeutic targets to overcome RA resistance in breast cancer." (PMID 26142905, 2015). "Furthermore, breast cancer cells with an elevated FABP5/CRABP2 ratio show increased resistance to RA." (PMID 26142905, 2015). "The patient data supports the role of FABP5 in breast cancer and TNBC." (PMID 25779666, 2015). "Since EGFR is highly expressed in TNBC breast cancer and EGFR has been associated with metastasis and mortality of TNBC, we analyzed a potential correlation of EGFR expression in our SFBCAS TMA with FABP5 expression." (PMID 25779666, 2015). "Sensitivity to RA is dependent on the expression level of FABP5 in mammary carcinoma cells." (PMID 25260874, 2014).
breast carcinoma (continued). "In light of the mounting evidence on the role of FABP5 in cancer cell lines, FABP5 may serve as a novel prognostic marker and inhibiting FABP5 can serve as a potential combinatorial treatment to sensitize mammary carcinoma cells to retinoid therapy." (PMID 25260874, 2014). "Not only are elevated levels of FABP5 a key determinant in the tumorigenic properties of mammary carcinoma, but also pancreatic cancer cell subtypes with elevated levels of FABP5 were associated with migration and invasion of cells, paralleling to lack of tumor growth inhibition." (PMID 25260874, 2014). "Hence, FABP5 is regulated by NF-κB in mammary carcinoma MDA-MB-231 cells and curcumin downregulates FABP5 expression by suppressing the p65 subunit of NF-κB." (PMID 25260874, 2014). "Identifying potential drug targets against FABP5 will establish the sensitivity of cancer cells to RA and may prove to be a rationale to improve the clinical outcome of RA use in breast cancer patients." (PMID 25260874, 2014). "The high expression level of FABP5 in the aggressive RA-resistant TNBC cells, MDA-MB-231 and MDA-MB-468, correlates with the marked upregulation of FABP5 observed in human breast tumors, particularly in tumors categorized by its invasive properties as well as late stages of breast cancer." (PMID 25260874, 2014). "The observations demonstrate that, similarly to effects observed in mammary carcinomas, activation of the FABP5/PPARβ/δ pathway induces PPARβ/δ target genes involved in cell survival and growth and enhances cell proliferation and anchorage-independent growth in prostate cancer cells." (PMID 20847935, 2010). "Inhibiting the activity of FABP4 and/or FABP5 may offer a novel strategy for breast cancer therapy." (PMID 40106183, 2025). "In colorectal and breast cancers, overexpression of FABP4 and FABP5 has been correlated with recurrence risk and chemoresistance, suggesting their utility in identifying high-risk patients who may benefit from intensified adjuvant treatment or early postoperative monitoring strategies." (PMID 40717587, 2025). "Targeting ATGL and FABP5 could provide new therapeutic strategies for patients with breast cancer." (PMID 29914512, 2018). "The ratio of FABP5/CRABP2 was previously demonstrated to be associated with ATRA resistance in gliomas, with prognostic behavior in pancreatic ductal adenocarcinoma cell lines, with activation of PPAR instead of RAR in a breast cancer mouse model and with tumor grade and prognosis in breast cancer." (PMID 29131833, 2017). "Moreover, we provide evidence that curcumin can inhibit FABP5 and the use of curcumin or its analogs may serve as potential therapeutic agents to overcome RA resistance in RA-resistant breast cancer cells." (PMID 25260874, 2014). "Thus, elevated levels of FABP4 and FABP5 may serve as poor prognostic markers for breast cancer." (PMID 40106183, 2025). "In this study, we collected surgical breast tissue samples from 96 women with different subtypes of breast cancer and comprehensively analyzed the expression pattens of FABP4 and FABP5." (PMID 40106183, 2025). "Approximately 30% more cells of the macrophage subtypes positive for LAM2_APOE, LAM1_FABP5 and EGR1, respectively, expressed CLEC10A in TNBC in comparison with ER+ / HER2+ breast cancer (Chi-squared p < 0.001)." (PMID 38206856, 2024). "In breast cancer, SBFI26, an inhibitor of FABP5, induces ferroptosis by elevating levels of ferrous ions and lipid peroxidation, increasing the expression of ALOXE3, ALOX5, and ALOX15, thus driving ferroptosis in tumor cells." (PMID 39633985, 2024). "Interestingly, previous reports have indicated that FABP5+ macrophages are likely to be a lipid‐associated macrophages (LAM) with similar characteristics to obese mice and human, particularly, the FABP5 overexpression is detrimental to the survival of breast cancer patients." (PMID 37021816, 2023).
breast carcinoma (continued). "We also found that breast cancer cells induce the transcription of different fatty acid transporters such as FABP4, FABP5 and CD36." (PMID 34884983, 2021). "Next, we determined the correlation between increased CD36 expression and the various FABP genes (FABP1, FABP2, FABP3, FABP4, FABP5 and FABP6) in the TCGA breast cancer cohort." (PMID 34561446, 2021). "First, the mRNA expression levels of FABP4,FABP5 and another putative FA translocase, CD36, were detected in various breast cancer cell lines." (PMID 29914512, 2018). "The ability of lipolysis in breast cancer cells were measured, as well as the expression of the rate-limiting lipase ATGL and fatty acid transporter FABP5." (PMID 29914512, 2018). "On the other hand, FABP5 has been reported to enhance the metastatic potential and tumorigenesis through activation of EGFR signaling pathway in breast cancer and induce the epithelial-mesenchymal transaction (EMT) in hepatocellular cancer." (PMID 29914512, 2018). "Fatty acid binding protein 5 (FABP5), an intracellular lipid binding protein, has been shown to play a role in various cancers, including breast cancer." (PMID 25779666, 2015). "We show FABP5 protein expression correlates with TNBC, high grade tumors, and worse disease-free survival in a tissue microarray containing 423 breast cancer patient samples." (PMID 25779666, 2015). "Our results suggest that CRABP1, in addition to the previously identified FABP5 and CRABP2, is a key factor regulating breast cancer cell response to RA." (PMID 26142905, 2015). "The expression and subcellular distribution of two RA-binding proteins, FABP5 and CRABP2, has already been shown to play critical roles in breast cancer cell response to RA." (PMID 26142905, 2015). "Because curcumin affects the expression level of FABP5 and PPARβ/δ in RA-resistant MDA-MB-231 mammary carcinoma cells, we further examined the effect of curcumin on these genes in RA-resistant MDA-MB-468 cells." (PMID 25260874, 2014). "We examined the expression level of FABP5 in RA-resistant TNBC cell lines (MDA-MB-231 and MDA-MB-468) in comparison to mammary carcinoma cells sensitive to RA-mediated growth suppression." (PMID 25260874, 2014). "Interestingly, in breast cancer tissue, we further observed that FABP4 remains primarily expressed in stromal adipocytes, endothelial cells and macrophages, whereas FABP5 is significantly upregulated in epithelial-derived tumor cells." (PMID 40106183, 2025). "Further investigation into the dynamics of specific FABPs, such as FABP5 and FABP4, and their differential expression in distinct stages of breast cancer could unveil nuanced regulatory mechanisms that impact TAM behavior." (PMID 38411356, 2024). "Consistently, FABP5 expression drives the proliferation of estrogen receptor (ER)-negative breast cancer cells on exposure to retinoic acid (RA), resulted in poor survival." (PMID 38653992, 2024). "In addition, several retinoic acid transport proteins have been found to correlate with increase pancreatic cancer cell motility and invasion, including CRABP2 and FABP5, while CRABP1 correlates with worse prognosis in breast cancer." (PMID 37130839, 2023). "Second, we found that novel FABP5+ macrophages are detrimental to breast cancer survival rather than M2‐like macrophages that have been repeatedly reported." (PMID 37021816, 2023). "The results indicated that FABP5 and PPARβ/δ were the key mediators of EGFR’s ability to enhance cell proliferation, further confirming that PPARβ/δ acted as a tumor-promoting factor playing a role in breast cancer." (PMID 36611922, 2022). "However, FABP5 has been reported to enhance EMT, metastatic potential and tumorigenesis through activation of the EGFR signaling pathway in breast cancer and induce EMT in hepatocellular cancer." (PMID 33352874, 2020).
breast carcinoma (continued). "While our current study supplements previous findings, how adipocytes promote the malignant progression of breast cancer cells via upregulated FABP5 has not been thoroughly elucidated, but subsequent research is now in progress." (PMID 29914512, 2018). "CRABP1 and FABP5 co-expression may serve as a predictive biomarker of ATRA resistance in this tumor type, and the downregulation may be a key step in (re)sensitizing breast carcinoma cells to retinoid therapy." (PMID 30384831, 2018). "Relative mRNA expression levels of FABP4, FABP5 and CD36 in breast cancer cell lines." (PMID 29914512, 2018). "Furthermore, we showed a direct correlation between high FABP5 expression and EGFR expression in breast cancer patients." (PMID 25779666, 2015). "FABP5 has been shown to play a role in breast cancer in an EGFR family member, HER2, however, not EGFR." (PMID 25779666, 2015). "Hence, similarly to its ability to enhance the proliferation of keratinocytes and to drive mammary tumor growth in the breast cancer mouse model MMTV-neu, the FABP5/PPARβ/δ pathway induces prostate cancer cell growth." (PMID 20847935, 2010). "Importantly, breast tissue itself is rich in lipids, so it is reasonable to believe that FABP5+ LAM may be a new tumor target following M2 like macrophages, especially in breast cancer." (PMID 37021816, 2023). "Previous studies have revealed that FABP5 and FABP7 might regulate lipid quality and/or quantity to promote aggressiveness such as cell growth, invasiveness, survival, and inflammation in breast cancer cells." (PMID 36230586, 2022). "A subsequent study on mammary carcinoma imputed to Kruppel-like factor 2 (KLF2) the shifting of ATRA signaling from the pro-oncogenic FABP5/PPARβ/δ path to the anti-carcinogenic CRABPII/RAR pathway, inducing the expression of CRABPII and inhibiting the expression of FABP5 and PPARβ/δ." (PMID 32012980, 2020). "Additionally, many markers we observed that defined our monocyte clusters (FABP5, FN1, IL1RN, CCL3, CCL4, CXCL8, CXCL3, IL1B) during transient, short-term CM stimulation, were elevated in either PD-L1pos or PD-L1neg TAMs isolated and sequenced from breast cancer." (PMID 40176808, 2025). "However, the significant inhibitory effect of ATPR on the proliferation, invasion, and migration of breast cancer cells may not be directly related to the ratio of CRABP2/FABP5." (PMID 34632074, 2021). "However, the FABP5/CRABP2 ratio does not always predict breast cancer cell response to RA, and RA resistance in the squamous cell carcinoma cell line COLO 16 cannot be overcome by either restoration of CRABP2 expression or an increased CRABP2/FABP5 ratio, indicating that other factors are involved." (PMID 26142905, 2015). "Relapse-free survival (%RFS) indicated that FABP4 (p = 0.015) and FABP5 expression (p = 0.075) correlated with TNBC occurrence and decreased survival, but not in hormone positive mammary tumors." (PMID 31941087, 2020). "However, a more recent study indicated that FABP5 depletion in PCa (PC3) and breast cancer (MDA-MB-231) cell lines promoted, rather than suppressed, lipid droplet formation, suggesting an inhibitory effect of FABP5 on fatty acid storage in lipid droplets." (PMID 33352874, 2020). "Although it was shown that FABP5 mRNA is expressed in TNBC patient samples and predicts worse prognosis, a detailed analysis of its protein expression and especially its correlation with EGFR has not been extensively studied in breast cancer, especially TNBC." (PMID 25779666, 2015).
prostate carcinoma (61 papers, 2008 to 2025). A carcinoma that arises from epithelial cells of the prostate gland. "High FABP5 expression is significantly associated with poor prognosis in prostate cancer patients, and FABP5 inhibitors (e.g., SBFI-26) suppress tumor cell proliferation and invasion." (PMID 40717587, 2025). "In other solid tumors, FABP5 promotes the malignant proliferation and metastasis of tumor, such as prostate cancer, breast, cancer, and liver cancer, and are associated with prognosis." (PMID 38956267, 2024). "Their findings further support the potential of FABP5 as a diagnostic and prognostic marker in prostate cancer." (PMID 38201450, 2023). "Fatty acid binding protein 5 (FABP5) is an intracellular lipid chaperone that is upregulated in advanced prostate cancer and is implicated as a key driver of its progression." (PMID 37796964, 2023). "Significantly enough, emerging evidence suggests that fatty acid-binding protein 5 (FABP5) in extracellular vesicles is significantly associated with Gleason score in prostate cancer patients." (PMID 34576294, 2021). "After its crucial activity in promoting malignant progression in cancer cells was initially demonstrated, increased FABP5 expression in archival prostate cancer tissues is found to be significantly associated with a reduced patient survival time." (PMID 28415688, 2017). "Univariate logistic analysis showed that FABP5 was significantly associated with prostate cancers with GS 7 or more (p-value < 0.001)." (PMID 28211531, 2017). "Even after adjusting for age, PSA, and PSA density, FABP5 was significantly associated with prostate cancer with GS 7 or more (p-value = 0.003)." (PMID 28211531, 2017). "Higher levels of both nuclear and cytoplasmic FABP5 in prostate carcinoma tissues are significantly associated with a reduced patient survival." (PMID 26814431, 2016). "Apart from prostate cancer, FABP5 has also been implicated in malignancies of bladder, pancreas, breast and glioblastoma." (PMID 26814431, 2016). "In this study, we have investigated whether FABPs other than FABP5 can be used as diagnostic or prognostic markers; these may be involved in initial development and in malignant dissemination of prostate cancer cells." (PMID 27779102, 2016). "Among FABPs, FABP5 was shown to be overexpressed in several tumor types and its expression level was shown to be associated with the growth and metastasis of several cancer types including prostate cancer, intrahepatic cholangiocarcinoma, colorectal cancer and cervical cancer." (PMID 39940783, 2025). "FABP5 promotes prostate cancer proliferation and invasion by regulating lipid metabolism and the PPARγ signaling pathway." (PMID 40717587, 2025). "This study aims to investigate the mechanism of action of a newly developed compound (SBFI-1143) targeting Fatty acid-binding protein 5 (FABP5), shown to play a critical role in prostate cancer development and progression." (PMID 41374926, 2025). "In contrast, deleting FABP5 generated similar consequences as deleting the androgen receptor (AR) in prostate cancer cells, a major driver of the disease progression." (PMID 41374926, 2025). "In support of this, it was shown that FABP5 induced an increase of proliferation, tumorigenicity and metastasis in prostate cancer, and thus an elevated level of FABP5 has been identified as a poor prognostic indicator in cancers." (PMID 39273233, 2024). "Similar phenomena are reported in prostate cancer, showing that FABP5 activates PPARγ and up-regulates VEGF29." (PMID 37416772, 2023). "Our study demonstrates a potential new function for FABP5 in regulating taxane sensitivity and the expression of a major P-glycoprotein efflux pump in prostate cancer cells." (PMID 37796964, 2023). "Previous work by us and others suggested that FABP5 functions as a major node in a prostate cancer lipid signaling network by linking cytoplasmic lipid production to nuclear receptor signaling." (PMID 38201488, 2023).